CDCA8 (cell division cycle associated 8)
Diseases named in the same sentence as CDCA8 in open-access papers (continued):
Sharing a sentence is not in itself a finding about the gene and the disease.
melanoma (9 papers, 2019 to 2025). A malignant, usually aggressive tumor composed of atypical, neoplastic melanocytes. "Investigating the effects of MYB proto-oncogene like 2 (MYBL2)-mediated regulation of Cell division cycle associated 8 (CDCA8) expression on the biological activity of cutaneous malignant melanoma cells." (PMID 38961953, 2024). "CDCA8 loss has been shown to decrease the malignant behavior of melanomas through the ROCK signaling pathway." (PMID 36639822, 2023). "Despite previous indications from our research suggesting the potential involvement of CDCA8 overexpression in melanoma pathogenesis, the regulatory mechanisms governing CDCA8 remain elusive." (PMID 38961953, 2024). "We arrived at such a conclusion that MYBL2 promoted the migration, invasion and proliferation ability of cutaneous malignant melanoma cells by targeted regulation of CDCA8 expression in this study." (PMID 38961953, 2024). "To investigate the regulatory mechanism of MYBL2 on CDCA8 expression in human malignant melanoma cells, we transfected MYBL2, CDCA8 genes, and their co-overexpression and knockdown plasmids into A375 cells." (PMID 38961953, 2024). "From this, we inferred that TMED3 promotes the proliferation and migration of melanoma cells via targeting CDCA8." (PMID 36991473, 2023). "More importantly, we demonstrated that TMED3 promotes melanoma cell proliferation and migration through a mechanism that targets CDCA8 and involves the PI3K/AKT signaling pathway." (PMID 36991473, 2023). "Together with the outcomes of the in vitro experiments, these findings validate a direct association between MYBL2 and CDCA8 expression in the advancement of malignant melanoma cell proliferation and migration, and CDCA8 could be directly transcriptionally regulated by MYBL2." (PMID 38961953, 2024). "In an independent, publicly available RNA sequencing dataset of patient-derived melanoma samples, AURKA, AURKB, and CDCA8 showed trends toward increased expression in patients who did not respond to anti-PD-1 therapy (progressive disease)." (PMID 33123754, 2021). "In contrast, the vehicle samples of cell line M130227 predominantly upregulate factors that indirectly influence MAPK pathway activity through growth factor signaling and cell cycle progression, thereby promoting melanoma aggressiveness (e.g., PGF, CDCA8, DLGAP5, TPX2)." (PMID 41199020, 2025). "Both in that dataset and in an independent dataset of melanoma samples derived from patients treated with anti-PD-1 therapy, AURKA, AURKB, and CDCA8 expression were higher in tumors that did not respond to immunotherapy." (PMID 33123754, 2021).
prostate carcinoma (8 papers, 2019 to 2023). A carcinoma that arises from epithelial cells of the prostate gland. "As for the mechanism of CDCA8 overexpression, UAP1L1 is identified as a critical factor for CDCA8 expression, and promotes cell growth, migration, invasion, and apoptosis in prostate cancer." (PMID 36639822, 2023). "CDCA8 is upregulated in bladder and prostate cancer tissues, and knockdown of CDCA8 inhibits tumor cell proliferation." (PMID 37201027, 2023). "The results indicated that UAP1L1 promoted the proliferation, migration and invasion of prostate cancer cells, which was inhibited by downregulating CDCA8." (PMID 35168617, 2022). "Here we reported the study of UAP1L1 in prostate cancer and provide evidence that UAP1L1 has a critical role in tumorigenesis through targeting CDCA8, which is essential for the growth of at least two prostate cancer cell lines." (PMID 35168617, 2022). "The immunohistochemical staining results indicated CDCA8 had higher expression level in prostate cancer tissue than normal prostatic tissues." (PMID 35168617, 2022). "In the present study, the results of cell function experiments suggested that the downregulation of CDCA8 inhibited the proliferation and migration of prostate cancer cells and promoted apoptosis." (PMID 35168617, 2022). "But the inhibitory effect of shCDCA8 would be weakened, when prostate cancer cells overexpressed UAP1L1 as well as knocked down CDCA8." (PMID 35168617, 2022). "The effects of CDCA8 on prostate cancer cells were also verified in vitro, which was through detecting the change of proliferation, migration, invasion and apoptosis of prostate cancer cells after CDCA8 knockdown." (PMID 35168617, 2022). "In conclusion, the results in this study revealed that UAP1L1 promoted the progression of prostate cancer through the downstream gene CDCA8." (PMID 35168617, 2022). "CDCA8 was reported as a potential prognostic biomarker for a variety of cancers, including breast, liver, and prostate cancer." (PMID 35884419, 2022). "In the latest published study on biomarkers of prostate cancer, hub genes such as KIF20A and CDCA8 are associated with adverse BCR-free survival of PCa patients and have better specificity and sensitivity in the diagnosis of prostate cancer." (PMID 31565099, 2019). "Future studies could further investigate how CDCA8 promotes prostate cancer proliferation and metastasis." (PMID 35449575, 2022). "Besides, the overexpression of UAP1L1 promoted the proliferation and migration of prostate cancer cells, which also alleviated the inhibitory effects of CDCA8 knockdown on prostate cancer progression." (PMID 35168617, 2022). "Therefore, UAP1L1/CDCA8 can be used as potential therapeutic target for prostate cancer, providing a new possible strategy for the diagnosis and treatment of prostate cancer." (PMID 35168617, 2022). "UAP1L1 knockdown reduced CDCA8 expression in prostate cancer cells." (PMID 35168617, 2022). "Furthermore, the expression of CDCA8 was upregulated in prostate cancer tissues and inhibited by UAP1L1 knockdown." (PMID 35168617, 2022). "In the genes of the MEmagenta module, we found that the known genes closely related to cancer stemness in non-prostate cancer, such as BRCA1, EZH2, FOXM1, CDC20, and CDCA8, were all clustered in this module, indicating these genes were also closely related to the stemness of prostate cancer cells." (PMID 33985534, 2021). "The UAP1L1 overexpression, CDCA8 knockdown and UAP1L1 overexpression accompanied by CDCA8 knockdown cell models were constructed successfully in vitro by lentivirus transfection in order to investigate the effects of CDCA8 regulated by UAP1L1 on prostate cancer cells." (PMID 35168617, 2022). "However, the exact function of CDCA8 in the development and progression of prostate cancer (PCa) remains unclear." (PMID 35449575, 2022).
prostate carcinoma (continued). "Besides, the regulation mechanism of UAP1L1 in prostate cancer was explored preliminarily, which revealed that UAP1L1 promoted prostate cancer progression by regulating CDCA8." (PMID 35168617, 2022). "However, the specific role of CDCA8 in prostate cancer was not confirmed in experiments." (PMID 35168617, 2022).
glioma (7 papers, 2021 to 2024). A benign or malignant brain and spinal cord tumor that arises from glial cells (astrocytes, oligodendrocytes, ependymal cells). "our study reveals a new underlying mechanism of CDCA8 in glioma." (PMID 33542211, 2021). "And we further screened target genes of CDCA8 and investigated the potential role of CDCA8 synergized with the transcription factor E2F1 in glioma cell proliferation and migration, indicating the underlying molecular mechanism of CDCA8/E2F1-associated tumor suppression in glioma treatment." (PMID 33542211, 2021). "Combined with the GDSC drug database, CDCA2, CDCA4, CDCA5, CDCA7, and CDCA8 have potential as clinical drug treatments for glioma." (PMID 38181024, 2024). "And subsequent multivariate COX regression analyses suggested that CDCA2, CDCA5, and CDCA8 were independent prognostic factors for glioma." (PMID 38181024, 2024). "CDCA2, CDCA4, CDCA5, CDCA7, and CDCA8 showed high accuracy for diagnosing gliomas, with CDCA7 having the highest accuracy (AUC: 0.982)." (PMID 38181024, 2024). "CDCA8 acts as a cell cycle regulator and tumor promoter in gliomas and promotes tumor cell proliferation." (PMID 35774141, 2022). "CDCA8 knockdown inhibited glioma cell proliferation (P < 0.001) and induced glioma cell apoptosis (P < 0.001)." (PMID 33542211, 2021). "This study provides a novel mechanistic basis and strategy for clinical application of CDCA8/E2F1 in glioma in the future." (PMID 33542211, 2021). "To assess the effect of CDCA8 on glioma cell viability, apoptosis, cycle distribution, and migration, we used lentivirus vector to silence the CDCA8 expression in SHG-44 and U251 cells." (PMID 33542211, 2021). "In conclusion, despite the limited numbers of clinical specimens and relatively preliminary mechanism research, we defined CDCA8 as a novel tumor promotor in the development of glioma probably through regulating E2F1." (PMID 33542211, 2021). "This phenotype demonstrated that overexpression of CDCA8 promoted glioma cell proliferation (P < 0.01) and migration (P < 0.001), while inhibiting cell apoptosis (P < 0.01)." (PMID 33542211, 2021). "In vitro and in vivo investigations demonstrated that CDCA8 promoted the glioma malignancy by promoting cell proliferation, cell migration, and inhibiting cell apoptosis." (PMID 33542211, 2021). "In our study, we found that CDCA8 promoted glioma cell proliferation by inhibiting cell apoptosis and cell cycle arrest, and enhanced cell migration." (PMID 33542211, 2021). "All these results implied the carcinogenic effect of CDCA8 on glioma progression, which was consistent with our previous results." (PMID 33542211, 2021). "Moreover, we found that CDCA8 not only had significant clinical correlations with important clinical features of glioma patients, including WHO grade, IDH status, and 1p/19q codeletion, but also had good diagnostic efficacy." (PMID 38181024, 2024). "CDCA2, CDCA3, CDCA4, CDCA5, CDCA7, and CDCA8 were significantly highly expressed in glioma samples." (PMID 38181024, 2024). "CDCA8 silencing also suppressed cell growth, migration, and invasiveness in gliomas." (PMID 36639822, 2023). "Given E2F1 as oncogene in glioma and our microarray analysis, we deduced that E2F1 may mediate the effect of CDCA8 in glioma." (PMID 33542211, 2021). "CDCA8 is upregulated in glioma and could be considered as a promising target for cancer therapy based on gene silencing." (PMID 33542211, 2021). "And clinical data showed that CDCA8 may act as a biomarker for the progression and prognosis of glioma." (PMID 33542211, 2021). "We showed that CDCA8 effectively inhibited cell cycle arrest and cell apoptosis in glioma." (PMID 33542211, 2021). "Altogether, CDCA8 knockdown exhibits anti-glioma properties in vivo." (PMID 33542211, 2021). "Synergized with E2F1, CDCA8 promoted glioma cell proliferation and migration in vitro and vivo." (PMID 33542211, 2021).
glioma (continued). "In this study, we demonstrated that high expression of CDCA8 was associated with advanced WHO grade III–IV and poor overall and disease-free survival, indicating CDCA8 may be a biomarker for the high-grade glioma patients’ disease progression and prognosis." (PMID 33542211, 2021). "In the present study, we demonstrated the prognostic role of CDCA8 in high-grade glioma." (PMID 33542211, 2021). "The expression of CDCA8 was generally higher in glioma tissues." (PMID 33542211, 2021). "Thus, CDCA8/E2F1 axis is responsible for glioma cell growth and migration in vitro or in vivo." (PMID 33542211, 2021). "To determine whether the CDCA8 expression is correlated with the malignant progression and clinical outcomes of gliomas, we detected the CDCA8 level in glioma IHC samples and evaluated the overall survival and disease-free survival outcomes by Kaplan–Meier survival analysis." (PMID 33542211, 2021). "Moreover, CDCA8 exhibited its carcinogenetic role in glioma cell growth and migration in vitro and vivo, silence of which could be a promising strategy to suppress glioma progression." (PMID 33542211, 2021). "In this study, we revealed that CDCA8 synergized with E2F1 facilitated the proliferation and migration of glioma." (PMID 33542211, 2021). "CDCA8, in combination with E2F1, accelerates glioma proliferation and migration." (PMID 36855818, 2023). "As the potential downstream of CDCA8, knockdown of E2F1 could alleviate or reverse the glioma growth induced by CDCA8 overexpression." (PMID 33542211, 2021). "The interaction between CDCA8 and E2F1 verified by co-IP assay showed that CDCA8 may regulate the progression of glioma through interacting and regulating E2F1." (PMID 33542211, 2021). "Furthermore, we confirmed the translation expression level of the hub genes using the HPA database, and the prognostic biomarkers were found to be stained strongly or moderately.: SMC4, OCR1, CDCA8, and DLGAP5, indicating that these hub genes were translated more in glioma samples." (PMID 38926605, 2024). "Moreover, the results of co-IP assay indicated that CDCA8 and E2F1 may act as coregulators in glioma malignancy." (PMID 33542211, 2021). "Notably, the biological function of CDCA8 has not been extensively investigated in glioma." (PMID 33542211, 2021).
lung adenocarcinoma (6 papers, 2013 to 2023). A carcinoma that arises from the lung and is characterized by the presence of malignant glandular epithelial cells. "Studies had revealed that MiR-133a-3p played crucial roles in the regulation of CDCA8 in oesophageal cancer, and miR-133b regulated the CDCA8 expression in lung adenocarcinoma through a post-transcriptional regulation manner." (PMID 37201027, 2023). "For CDCA8, in Hou's dataset, the fold changes in lung adenocarcinoma, SCC, and large-cell LC were 2.935, 3.743, and 4.913, respectively, compared with normal tissues." (PMID 32104702, 2020). "Moreover, CDCA8 participates in pancreatic ductal adenocarcinoma and lung adenocarcinoma tumor progressions." (PMID 36855818, 2023). "Moreover, miR-133b suppressed cell proliferation, motility, and invasion in lung adenocarcinoma by targeting CDCA8." (PMID 35354488, 2022).
pancreatic ductal adenocarcinoma (5 papers, 2021 to 2025). An infiltrating adenocarcinoma that arises from the epithelial cells of the pancreas. "In pancreatic ductal adenocarcinoma, CDCA8 mediates the upregulation of KIF18B and promotes tumour cell proliferation." (PMID 34741389, 2021). "In pancreatic ductal adenocarcinoma, CDCA8 promotes tumor cell proliferation." (PMID 35449575, 2022). "In addition, the CDCA8 has been proved could promote the proliferation and invasion of pancreatic ductal adenocarcinoma by activating CD44." (PMID 40465781, 2025).
gastric cancer (4 papers, 2018 to 2023). A primary or metastatic malignant neoplasm involving the stomach. "High expression of CDCA8 may lead to poor prognosis in patients with lung and gastric cancer." (PMID 36147508, 2022).
Clear Cell Renal Cell Carcinoma (3 papers, 2021 to 2025). "CDCA8 was highly expressed in various malignant tumors, including adrenocortical carcinoma (ACC), cholangiocarcinoma (CHOL), renal clear cell carcinoma (KIRC), and so on (p < 0.05)." (PMID 36855818, 2023).
endometrial carcinoma (3 papers, 2022 to 2024). A malignant tumor arising from the epithelium that lines the cavity of the uterine body. "The expression of microRNA (miR)-524-5p reduced the migration and invasion of Ishikawa endometrial carcinoma (EC) cells, while decreasing BUB1, BUB1B, CCNA2, and CDCA8 expression." (PMID 37853361, 2023).
pancreatic cancer (3 papers, 2022 to 2023). "Given that CDCA8 promoted the proliferation and migration of pancreatic cancer cells in vitro and in vivo, we next sought to explore the underlying mechanisms by focusing on the relationship between CDCA8 and CD44 expression." (PMID 36358852, 2022). "We confirmed the interaction between KNTC1 and cell division cycle associated 8 (CDCA8) by immunoprecipitation, which indicates that KNTC1 interacts with CDCA8 in pancreatic cancer." (PMID 35852618, 2023). "KIF18 was found to bind to the promoter region of CDCA8 and enhance CDCA8 expression, as well as increase cell proliferation capacity in pancreatic cancer." (PMID 36639822, 2023). "Previous studies have shown that KIF18B promotes pancreatic cancer cell proliferation by activating CDCA8 in in vitro assays." (PMID 36358852, 2022). "In conclusion, we discovered that CDCA8 silencing inhibited the proliferation of pancreatic cancer cells in vivo." (PMID 36358852, 2022). "CDCA8 has been previously shown to promote pancreatic cancer cell proliferation and invasion." (PMID 36358852, 2022). "In this study, the specific mechanism by which the CDCA8 contributes to pancreatic cancer progression via the activation of CD44 was clarified, and CDCA8 knockdown inhibited the proliferation and metastasis of pancreatic cancer." (PMID 36358852, 2022).
thyroid dysgenesis (3 papers, 2017 to 2025). "In a cohort of patients with thyroid dysgenesis, homozygous CDCA8 mutations were identified in two cases within a blood-related family and heterozygous in two other sporadic cases." (PMID 41303336, 2025). "Recently, genetic variants in CDCA8 (also called BOREALIN) were identified in a study of three consanguineous families with thyroid dysgenesis." (PMID 29026407, 2017). "Thus, the potential mechanistic role of CDCA8 in thyroid dysgenesis is still unclear, and the range of thyroid phenotypes observed in patients carrying CDCA8 variants is broad, ranging from thyroid agenesis or ectopy to euthyroid individuals with asymmetric thyroid lobes or thyroid nodules." (PMID 29026407, 2017).
diabetes (2 papers, 2022). "Nonetheless, none of the expression of ASPM, CDC20, DLGAP5, BUB1B, CDCA8, and NCAPG was related to BMI and diabetes." (PMID 36186000, 2022).
lymphoma (2 papers, 2024 to 2025). A malignant (clonal) proliferation of B- lymphocytes or T- lymphocytes which involves the lymph nodes, bone marrow and/or extranodal sites. "Similarly, the suppression of BUB3, CCNB1, CDCA8, and CDK1 supported mitotic disruption and proliferative collapse in the HKB-11 lymphoma cells upon treatment with the N and UB combination." (PMID 40725093, 2025).
osteosarcoma (2 papers, 2020 to 2023). A usually aggressive malignant bone-forming mesenchymal neoplasm, predominantly affecting adolescents and young adults. "For example, CDCA8 was identified as a key gene in osteosarcoma, it and other hub genes were mainly enriched in PI3K-Akt signaling pathway." (PMID 36991473, 2023).